CDKN1A (cyclin dependent kinase inhibitor 1A)
Diseases named in the same sentence as CDKN1A in open-access papers (continued):
Sharing a sentence is not in itself a finding about the gene and the disease.
epilepsy (5 papers, 2018 to 2022). A brain disorder characterized by episodes of abnormally increased neuronal discharge resulting in transient episodes of sensory or motor neurological dysfunction, or psychic dysfunction. "TGF-β and CDKN1A-related pathways are common targets of epilepsy-associated miRNA." (PMID 35625943, 2022). "In support of the critical role of TGF-β signaling in epilepsy, several studies have discovered the downstream target gene CDKN1A as a central hub in epileptogenesis." (PMID 35625943, 2022). "An integrative analysis of epilepsy animal models and human epilepsy tissue found that CDKN1A is a central hub in epileptogenesis." (PMID 34287356, 2021). "mRNA levels of TGF-β and CDKN1A are upregulated in the cortex of patients with epilepsy." (PMID 35625943, 2022). "An integrative analysis of epilepsy animal models and human epilepsy tissue found five key genes, including TGF-β and CDKN1A, as central nodes in the protein networks in epileptogenesis." (PMID 35625943, 2022). "Consistent with their studies, we also observed downregulation of anti-apoptotic genes (CDKN1A, YWHAB, etc.)and upregulation of pro-apoptotic genes (BCLAF1, etc.)in human epilepsy samples." (PMID 34867172, 2021). "The results of KEGG showed that Cdkn1a is closely related to the HIF-1 signaling pathway, and dysregulated HIF-1 signaling may play a role in the pathogenesis of epilepsy in hippocampus." (PMID 35095492, 2021). "However, there has been no report on the exact role of CDKN1A in epilepsy, and CDKN1A has not been investigated in the context of TGF-β signaling." (PMID 35625943, 2022).
myocardial infarction (5 papers, 2021 to 2024). Gross necrosis of the myocardium, as a result of interruption of the blood supply to the area, as in coronary thrombosis. "The myocardial infarction-related exosomes miR-208b and miR-208b regulate the growth of HUVECs by regulating CDKN1A expression." (PMID 38360841, 2024). "In addition, there are limited data on the expression of CDKN1A in LV remodelling, so further studies are needed to assess its potential role in LV remodelling after myocardial infarction." (PMID 39457420, 2024).
pituitary adenomas (5 papers, 2014 to 2022). "The presence of this SNV has not been previously explored in pituitary adenomas, although CDKN1A is downregulated in clinically non-functioning pituitary adenomas of gonadotrophic lineage but not in hormone-secreting tumors." (PMID 35563252, 2022).
pituitary tumor (5 papers, 2012 to 2019). A benign or malignant neoplasm affecting the pituitary gland. "This is an important observation as Rb1+/-; Cdkn1a-/- mice are susceptible to pituitary tumors and have similar survival as for Rb1G/+; Cdkn1b-/- animals, this indicates that the Rb1G mutation cooperates preferentially with p27 loss." (PMID 30703085, 2019). "Because Rb1G/G; Cdkn1b-/- mice develop pituitary tumors with complete penetrance, we also inspected whole mount views of pituitary glands to search for even subtle signs of overgrowth in Rb1G/G; Cdkn1a-/- mice at survival endpoints." (PMID 30703085, 2019). "In conjunction with prior results that Rb1G/G; Cdkn1b-/- animals succumb to pituitary tumors, and that Rb1+/-; Cdkn1a-/- mice have accelerated pituitary tumorigenesis, these genetic crosses provide two simple conclusions relating to RB function in cell cycle and cancer susceptibility." (PMID 30703085, 2019). "Recently, other germline mutations involving four cyclin-dependent kinase inhibitor genes (CDKN1A/p15, CDKN2C/p18, CDKN2B/p21 and CDKN1B/p27) and, in patients with pituitary tumors, the AIP gene have been found in a minority of patients with clear MEN1 phenotype." (PMID 23259638, 2012).
renal carcinoma (5 papers, 2018 to 2025). A carcinoma arising from the epithelium of the renal parenchyma or the renal pelvis. "A recent study supports a coordinate regulation of ZC3H12A/MCPIP1 and CDKN1A/p21 in a human renal carcinoma cell line." (PMID 32615986, 2020).
schizophrenia (5 papers, 2017 to 2024). A major psychotic disorder characterized by abnormalities in the perception or expression of reality. "In order to further explore the diagnostic value of the four hub genes (NFKBIA, CDKN1A, BTG2, and GADD45B) for schizophrenia, this experiment used ROC curves for evaluation." (PMID 35741729, 2022). "In this study, quetiapine inhibited the expression level of CDKN1A, which can also be used to explain the therapeutic effect of quetiapine on schizophrenia." (PMID 35741729, 2022). "Interestingly, all three highlighted miRNAs directly target CDKN1A, pointing to its possible function as a hub gene in the pathology of schizophrenia." (PMID 32194626, 2020). "Based on bioinformatics methods, this is the first study that found four hub genes closely related to schizophrenia (NFKBIA, CDKN1A, BTG2, and GADD45B)." (PMID 35741729, 2022). "In conclusion, NFKBIA, CDKN1A, BTG2, GADD45B, and the joint indicators of four hub genes have great potential as biomarkers and therapeutic targets for the diagnosis of schizophrenia." (PMID 35741729, 2022).
acute kidney injury (4 papers, 2015 to 2025). Sudden and sustained deterioration of the kidney function characterized by decreased glomerular filtration rate, increased serum creatinine or oliguria. "The Cdkn1a gene has also been found to be up-regulated shortly after acute renal failure." (PMID 26287527, 2015). "Furthermore, CDKN1A affects ischemia-induced acute renal failure." (PMID 34338139, 2021).
Alzheimer disease (4 papers, 2015 to 2025). A progressive, neurodegenerative disease characterized by loss of function and death of nerve cells in several areas of the brain leading to loss of cognitive function such as memory and language. "Autophagy deficiency promotes senescence-associated microglia as evidenced by reduced proliferation, increased CDKN1A and senescence-associated secretory phenotype in Alzheimer disease." (PMID 39988732, 2025). "In Alzheimer's disease Cdkn1a expression marks senescence like phenotype and inflammation." (PMID 36561300, 2022). "Inhibition of microglial autophagy leads to reduced cell proliferation and increased CDKN1A and SASP expression in a mouse model of Alzheimer disease." (PMID 39988732, 2025).
Burkitt lymphoma (4 papers, 2012 to 2021). A rare form of malignant mature B-cell non-Hodgkin lymphoma. "Previous studies showed that Pvt1 binds Cdkn1a and miR-149-3p to suppress their activity in primary chondrocytes and Burkitt lymphoma Rajit cells, respectively." (PMID 34364390, 2021).
esophageal squamous cell carcinoma (4 papers, 2017 to 2025). Esophageal squamous cell carcinoma (ESCC) is a type of esophageal carcinoma (EC) that can affect any part of the esophagus, but is usually located in the upper or middle third. "For instance, in ALKBH5 knockdown cells, the m6A level and stability of CDKN1A mRNA are upregulated, which enhances the expression of CDKN1A and suppresses the proliferation of esophageal squamous cell carcinoma (ESCC)." (PMID 40001461, 2025). "We then determined SOX2 and CDKN1A expression in lung and esophageal SCC cells after Ad-shSOX2 or Ad-ATF/SOX2 infection." (PMID 29262545, 2017). "In addition, the ATF more significantly suppressed cell viability and colony formation of SOX2-expressing lung and esophageal SCC cells compared to shSOX2, whereas little CDKN1A expression was induced after Ad-ATF/SOX2 infection in SOX2 negative lung SCC cells and normal human cells HUVEC and NHLF." (PMID 29262545, 2017). "We showed that ATF/SOX2 up-regulated CDKN1A, one of the target genes of SOX2, and induced cell G1 cycle arrest more effectively than shSOX2 in SOX2-expressing EBC2 lung cells and TE4 esophageal SCC cells." (PMID 29262545, 2017). "Ad-ATF/SOX2 up-regulated CDKN1A mRNA and protein expression more significantly than did Ad-shSOX2 in SOX2-expressing lung and esophageal SCC cells in vitro." (PMID 29262545, 2017). "Ad-ATF/SOX2 induced CDKN1A expression in all three kinds of SOX2-expressing lung and esophageal SCC cells but not in all five kinds of SOX2 negative cells." (PMID 29262545, 2017).
Hepatitis C (4 papers, 2023). "In addition, the six upregulated DETGs are involved in Hepatitis C, including CDKN1A, TRAF3, CXCL10, CASP3, EIF2S1, and IFIT1." (PMID 37107704, 2023).
myeloid leukemia (4 papers, 2020 to 2023). A clonal proliferation of myeloid cells and their precursors in the bone marrow, peripheral blood, and spleen. "CDKN1A has also been implicated in cell cycle arrest in response to PMA in U937 myeloid leukemia cells." (PMID 32719792, 2020). "A dose-rate-dependent induction of CDKN1A and GADD45A genes and other apoptosis-related genes occurs following low dose exposure in the human myeloid leukemia ML-1 cell line." (PMID 38162630, 2023).
polycystic ovary syndrome (4 papers, 2020 to 2025). A disorder that manifests as multiple cysts on the ovaries. "CDKN1A boosts up the cell division and cell cycle progression when targeted by an increased number of microRNA-93 in polycystic ovarian syndrome." (PMID 33490239, 2020). "In polycystic ovary syndrome, lnc-MAP3K13-7:1 inhibited the proliferation of ovarian GCs via DNMT1 downregulation mediated by CDKN1A promoter hypomethylation." (PMID 40214477, 2025). "In polycystic ovary syndrome (PCOS) patients, DNMT1-dependent CDKN1A promoter hypomethylation inhibits the proliferation and growth of GCs." (PMID 34175894, 2021).
Sepsis (4 papers, 2019 to 2025). Sepsis is defined as life-threatening organ dysfunction caused by a dysregulated host response to infection. "Sepsis, often complicated with hypoxia, which leads to cell cycle arrest, is linked to the transcription of CDKN1A." (PMID 38212812, 2024). "Interestingly, several of the genes linked to glucocorticoid signaling (Arl4d, Cdkn1a, Ddit4, Fkbp5, Gjb6, Il6ra, Klf15, Nfkbia, Rhob, Sdc4, Sgk1, Sult1a1, Tob2, Wipf3) and apoptotic process were still upregulated 4 days post-sepsis." (PMID 31278440, 2019). "GeneWalk analysis identified potential regulatory genes involved in sepsis, including IL1B, CDKN1A, CDK2, CSF3, and IL1R2, which were included among the SRGs." (PMID 40303348, 2025). "The boxplot revealed 26 differentially expressed genes between the sepsis-induced ALI and control samples: Ncf2, Slc2a6, Cd44, Txnip, Slc2a1, Ubc, Hspb1, Zfp36, Arntl, Ddit4, Tnfaip3, Txnrd1, Mt1, Hmox1, Gch1, Gclc, Stat3, Egfr, Hif1a, Bach1, Socs1, Dusp1, Cdkn1a, Fth1, Steap3, and Alox12." (PMID 37081490, 2023).
skin cancer (4 papers, 2012 to 2019). "In skin cancer cells, this treatment induced a global DNA demethylation, which was associated with elevated 5hmC levels in the CDKN1A promotor and increased p21cip1/waf1 expression." (PMID 31514410, 2019). "In these mice, DMBA/TPA treatment led to elevated expression of p21Cip1 and skin tumors could only be induced in the absence of p21Cip1, demonstrating that endogenous Myc has a critical function in repressing cdkn1a during skin tumor development." (PMID 22509363, 2012).
squamous carcinoma (4 papers, 2008 to 2022). "ACTL6A is reported to contribute to the repression of CDKN1A/p21CIP1 in squamous carcinomas, but no studies on its function in UC are available." (PMID 34885146, 2021). "Additional human microarray studies that assessed lung tissue from smokers, and tumor tissue from patients with AC and squamous cell carcinoma, another NSCLC, identified other unique genes such as Cdkn1a, cyclin-dependent kinase inhibitor 1A (P21), up in BALBLps-d." (PMID 19925653, 2009).
stomach cancer (4 papers, 2019 to 2022). "The expression of ACTA2, HIF1A, and VEGFA was independently associated with TJP1 in non-cancerous tissue, explaining 90% in its variability, and BCL2, HIF1A, CDKN1A, and PTGS2 were independently associated with TJP1 in gastric tumors, explaining 98% in gene variability." (PMID 32630408, 2020).
thyroid (4 papers, 2013 to 2022). "The findings that Cdkn1A and Bax mRNA were higher in the thyroid of ThrbPV/PVNcor1ΔID/ΔID than ThrbPV/PVNcor1+/+ mice provided us with a tool to further investigate the mechanisms by which NCOR1 regulated thyroid carcinogenesis." (PMID 23840792, 2013).
atrial fibrillation (3 papers, 2022 to 2025). A disorder characterized by an electrocardiographic finding of a supraventricular arrhythmia characterized by the replacement of consistent P waves by rapid oscillations or fibrillatory waves that vary in size, shape and timing and are accompanied by an irregular ventricular response. "GWAS also showed that variants in CDKN1A are associated with ischemic strokes, atrial fibrillation and cardioembolic stroke, while variants in other experimentally validated gene targets of mir-423-3p; PA2G4 are associated with BMI and BCL2L11 with T2DM and cholesterol levels." (PMID 36277770, 2022).
autoimmune disease (3 papers, 2016 to 2020). A disorder resulting from loss of function or tissue destruction of an organ or multiple organs, arising from humoral or cellular immune responses of the individual to their own tissue constituents. "CDKN1A, and GADD45a genes are, in essence, signal transducers that convert environmental and physiological stresses into various cellular stress responses including innate immunity, inflammation, and autoimmune diseases." (PMID 32695301, 2020).
bladder tumours (3 papers, 2001 to 2025). "In summary, clonal selection in normal bladder differs between men and women, mirrored by an increased number of mutations in RBM10 and CDKN1A in male bladder tumours." (PMID 41062697, 2025). "The number of bladder tumours with truncating mutations in RBM10 and CDKN1A is also significantly higher across men than women." (PMID 41062697, 2025). "Moreover, CDKN1A (p21) functions as a regulator of cell cycle progression at G1 phase and altered expression was demonstrated in more than half of pT1 bladder tumors." (PMID 23809295, 2013). "In addition, we found low CDKN1A expression by RT-PCR in bladder tumors from HCV infected patients." (PMID 23809295, 2013).
colorectal tumors (3 papers, 2009 to 2019). "For example, MYC was involved in the proliferation and oncogenesis of colorectal tumor cells through targeting lncRNAs CDKN1A and CDKN2B57." (PMID 30518750, 2018).
dermatitis (3 papers, 2019 to 2023). An inflammatory process affecting the skin. "HFD reduced mRNA levels of IL-17A, IL-17F, IL-22, IL-1β, tumor necrosis factor (TNF)-α, CXCL1, CXCL2, and keratin 16 and increased those of transforming growth factor (TGF)-β1 and cyclin-dependent kinase inhibitor 1A in imiquimod-induced dermatitis." (PMID 37762500, 2023). "The HFD decreased mRNA expression of IL-17A, IL-17F, IL-22, TNF-α, IL-1β, CXCL1, CXCL2, and keratin 16, and increased mRNA expression of TGF-β1 and CDKN1A in imiquimod-induced dermatitis." (PMID 37762500, 2023). "The HFD decreased mRNA expression of hyperproliferation-associated keratin 16 induced by imiquimod, and increased that of cell cycle inhibitor CDKN1A in imiquimod-induced dermatitis." (PMID 37762500, 2023). "In this prospective cohort study, we found that symptoms of dermatitis radiation, pain, pruritus and fatigue were associated with the expression level of some genes of the DNA-damage response pathway (FDXR, SESN1, XPC, ZMAT3, ATM, BCL2/BAX, and CDKN1A)." (PMID 31632918, 2019). "While the expression level of FDXR gene increased in patients experiencing a high grade of dermatitis radiation, those of SESN1, ATM, XPC, ZMAT3, CDKN1A genes decreased when radiation toxicity was manifested." (PMID 31632918, 2019).
endometriosis (3 papers, 2018 to 2024). The growth of functional endometrial tissue in anatomic sites outside the uterine body. "WNT4 was shown to be expressed in the normal peritoneum, suggesting that endometriosis can arise through a reversible transformation of the epithelium cells to endometriotic cells (metaplasia) through the developmental pathways associated with the HOXA9 and CDKN1A genes." (PMID 29937493, 2018).
Ewing sarcoma (3 papers, 2014 to 2023). A small round cell tumor that lacks morphologic, immunohistochemical, and electron microscopic evidence of neuroectodermal differentiation. "Thus, JIB-04 increases DNA damage, which in turn may be one, but not an exclusive, mechanism of CDKN1A induction in Ewing Sarcoma cells." (PMID 30237855, 2018).
fibrosis (3 papers, 2023 to 2025). the formation of excess fibrous connective tissue in an organ or tissue in a reparative or reactive process. "A high expression level of CDKN1A was strongly associated with the exacerbation of NAFLD fibrosis and predicted a poor prognosis in both animal experiments and human NASH samples, which was supported by our findings." (PMID 37305039, 2023). "In our study, VEGFA and CXCL8, in conjunction with CDKN1A, were the most upregulated genes in fibrosis patients." (PMID 37569323, 2023). "Hence, VEGFA, CXCL8, and CDKN1A, with a mild tendency to be upregulated in fibrosis patients, were markedly induced in the hyperfibrosis ones, with more pronounced signs of conjunctival fibrosis and very early failure of filtering surgery." (PMID 37569323, 2023).
Hyperinsulinemia (3 papers, 2023 to 2025). An increased concentration of insulin in the blood. "In contrast, CDH1 (FCHG, ins = 1.52), CDKN1A (FCHG, ins = 2.87), PTEN (FCHG, ins = 1.61) and MMP9 (FCHG, ins = 0.71) were slightly downregulated during hyperinsulinemia under the influence of a hyperglycemic environment, when compared to the respective untreated hyperglycemic control samples." (PMID 37313172, 2023). "BCL2L11 (FCHG, ins = 1.16), CDKN1A (FCHG, ins = 0.97) and TIMP2 levels (FCHG, ins = 1.50) were not affected by hyperinsulinemia." (PMID 37313172, 2023).
Hypoglycemia (3 papers, 2021 to 2023). A decreased concentration of glucose in the blood. "The purpose of this docking was to investigate whether the primary bioactive constituents of the compound played a role in hypoglycemia through the compound's key targets, which were CDK2, E2F1, CDKN1A, CDK1, and CCND1 and CCNB1." (PMID 36846049, 2023).
medulloblastoma (3 papers, 2009 to 2017). A malignant, invasive embryonal neoplasm arising from the cerebellum. "Based on these data, we determined the prevalence of genetic polymorphisms of CDKN1A in a sample of 10 ependymomas, 16 medulloblastomas and 15 astrocytomas from the northwestern part of the State of São Paulo, compared with 161 control subjects." (PMID 20169278, 2009).